ENSG00000261717 (novel TMEM170A-CFDP1 readthrough protein)
Gene: Protein-coding gene on chromosome 16 (75,412,684 to 75,464,706, reverse strand). Ensembl gene ENSG00000261717.
Genetic constraint (gnomAD): Loss-of-function variants: 17 observed, 14.41 expected, observed/expected ratio (o/e) 1.18, 90% interval 0.81 to 1.73. The synonymous counts are far from expectation, so gnomAD's model fits this gene poorly and the ratio says little. Missense variants: 195 observed, 148.64 expected, observed/expected ratio (o/e) 1.31, 90% interval 1.17 to 1.48. Synonymous variants: 91 observed, 62.36 expected, observed/expected ratio (o/e) 1.46, 90% interval 1.23 to 1.74.